EPO (erythropoietin)
Diseases named in the same sentence as EPO in open-access papers (continued):
Sharing a sentence is not in itself a finding about the gene and the disease.
anemia (continued). "Anemia in CKD is predominantly caused by a relative deficiency of erythropoietin, a hormone produced in adults primarily by the kidneys, although shortened red blood cell half-life and functional iron deficiency also contribute to the anemia of CKD." (PMID 32143582, 2020). "The fact that anemia in CKD develops even despite of elevated EPO levels may also result from peripheral EPO hyporesponsiveness or resistance caused by inflammation or secondary hyperparathyroidism." (PMID 33392212, 2020). "The decreased serum level of EPO is a main cause of CKD-associated anemia." (PMID 32635646, 2020). "Recombinant human erythropoietin is used to treat anemia in low‐risk MDS patients." (PMID 31755660, 2020). "On the one hand, reduced production of erythropoietin in the kidney is a cause of anemia." (PMID 31615569, 2019). "The mechanisms of dysregulation of iron metabolism, impaired growth of erythroid progenitor cells, and reduced erythropoietin response due to inflammation of chronic diseases are known to cause anemia with increasing red blood cell distribution width (RDW) and fluctuation in hemoglobin levels." (PMID 31754187, 2019). "Erythropoietin concentration is associated with malaria-related anaemia." (PMID 30894794, 2019). "In cancer, several cytokines namely tumor necrosis factor -α (TNF-α), transforming growth factor -β (TGF-β), interleukin-1 (IL-1), IL-6 and interferon-γ interfere normal erythrocyte production by modulating iron metabolism and blunting erythropoietin effect thereby causing anemia." (PMID 31387568, 2019). "Around the time that EPO received FDA approval in 1989 for treatment of anemia in chronic renal disease, death associated with EPO doping was suspected in eighteen young professional cyclists who died from unknown causes." (PMID 32038269, 2019). "Therefore, we conducted a prospective cohort study in type 2 diabetic patients with anemia to assess the association of EPO levels with renal outcomes." (PMID 31619722, 2019). "It is unknown whether anemia, iron deficiency, and/or reduced EPO are causal factors in the development of HFpEF or mere markers of CKD." (PMID 31551803, 2019). "It has been largely believed that neonatal anemia seen in early periods after birth may be caused by the reduction or complete loss of EPO synthesis and secretion from the placenta." (PMID 29916217, 2019). "Furthermore, anemia induces renal changes, leading to lower erythropoietin levels as well as increasing the risk of neural degeneration, as this hormone has neuroprotective effects in situations of hypoxia." (PMID 31591353, 2019). "Therefore, the loss of EPO production in the mouse fetal liver results in embryonic death due to severe anemia." (PMID 31245372, 2019). "The fact that hypogonadism is a well-established cause for anemia and reduced responsiveness to EPO in men with CKD may suggest a possible role for T therapy as an adjunct or an alternative to EPO in some men with CKD-related anemia." (PMID 31798530, 2019). "Collectively, these results provide convincing evidence for JPYS decoction in ameliorating CKD-associated anemia, and its mechanism might be related to regulate EPO production via HIF signaling pathway." (PMID 30941190, 2019). "Since iron deficiency and inflammation (reflected by CRP) are well-known causes of anemia and these factors have positive relationships with EPO levels, we excluded patients with iron deficiency (i.e., ferritin levels ≤50 ng/dL) and elevated CRP (greater than the median value)." (PMID 31619722, 2019). "Iron deficiency anemia (IDA) is a common problem, which causes resistance to erythropoietin-stimulating agents (ESAs), is associated with patients on chronic hemodialysis (HD), and increases morbidity and mortality, whereas correction of anemia improves these events in HD patients." (PMID 29596361, 2018).
anemia (continued). "In addition, there is a possibility that the clinical and demographic characteristics of the ESRD population continued to change, and treating anemia with erythropoietin or blood transfusion was associated with DVT." (PMID 30115029, 2018). "Additionally, studies have demonstrated that EPO can have neuroprotective effects, the production of EPO can be stimulated by anemic hypoxia in the brain, and anemia is an independent risk factor of cognitive decline." (PMID 30429775, 2018). "The pathogenesis of lymphoma-associated anemia is multifactorial and may include BM dysfunction, problems with iron reutilization, and an inadequate erythropoietin response." (PMID 29589833, 2018). "EPO was originally seen as potential treatment of sepsis-associated anemia." (PMID 29977234, 2018). "Anemia may occur and is disproportionately severe in relation to their renal function, and is thought to be linked to erythropoietin (EPO) deficiency." (PMID 29578399, 2018). "Relative deficiency of EPO is the predominant cause of anemia in CKD." (PMID 30108502, 2018). "Although the level of hepatic EPO production is weak and insufficient to compensate for anemia in CKD, stimulating hepatic EPO by pharmacologic HIF stabilization is sufficient to improve anemia in models of anemia caused by either renal insufficiency or chronic inflammation." (PMID 30108502, 2018). "The most known cause of CKD anemia is an insufficient erythropoietin (EPO) production." (PMID 29615029, 2018). "However, after the release on the market of the recombinant human EPO (r-HuEPO) in the 1990s and the decline in blood transfusions, iron deficiency started to emerge as an important cause of anemia in CKD patients." (PMID 29357391, 2018). "50% of women with anemia of chronic disease and iron deficiency (3/6) responded well to intravenous iron, and 67% (4/6) responded well to the combination of intravenous iron and recombinant human erythropoietin." (PMID 29348938, 2017). "Similarly, randomized trials have shown that overtreatment of anemia (Hgb greater than 12 g/dL) in patients with chronic kidney disease is associated with increased mortality, partly due to increased erythropoietin." (PMID 29216894, 2017). "Erythropoiesis stimulating agents (ESAs), the active ingredients of whichare recombinant human erythropoietin or its modified form, have been widely used to treat patients with certain kinds of anemia, for example chronic kidney disease-associated anemia, in clinical practice." (PMID 28819889, 2017). "Since EPO was first purified from urine more than three decades ago, its recombinant form has become widely used for the treatment of anemia associated with chronic kidney disease, human immunodeficiency acquired immune deficiency syndrome (HIV/AIDS), and cancer." (PMID 28415825, 2017). "Apart from this, there are some other factors that may influence the bone marrow function in patients with PC, such as castration and androgen blockage, which have been shown to cause anemia and could be corrected with recombinant erythropoietin." (PMID 28903443, 2017). "The main cause of anemia in CKD is insufficient production of erythropoietin by kidney." (PMID 28487874, 2017). "The anemia of CKD is due to many factors including decrease in erythropoietin secretion, iron, folic acid and vitamin B12 deficiency, decrease of life time of red blood cells, uremic toxicity, chronic and inflammatory diseases, infections and aluminum toxicity." (PMID 28042550, 2017). "Pale mucosa results from anemia mainly developed following the inability of the failing kidneys to secrete erythropoietin, loss of red blood cells through dialysis, increased brittleness of red blood cells and their early destruction and, in some cases, from malnutrition." (PMID 28210437, 2017). "Therefore, for CKD patients, with the progression of chronic kidney injury and renal function loss, anemia is a common complication predominantly resulting from the deficiency of renal EPO production." (PMID 28468297, 2017).
anemia (continued). "EPO, hemoglobin and eGFR for each category of anemia etiology compared to iron deficiency anemia." (PMID 27310832, 2016). "The differences observed are, though, certainly compatible with a direct effect of iron deficiency, and fit well with the observation that erythropoietin levels are considerably higher for a given [Hb] in the setting of iron deficiency anemia than anemias of other etiologies." (PMID 27140401, 2016). "Anemia in EB is thought to stem from chronic mucocutaneous inflammation, blood loss through skin wounds, and compromised bone marrow response to the elevated levels of erythropoietin." (PMID 28492007, 2016). "Giving the diagnosis of low risk MDS with isolated anemia, we checked serum erythropoietin level, that resulted in the reference range but inadequate for the degree of anemia (31.7 mUI/mL), therefore we started the patient on recombinant erythropoietin, 40000 U weekly." (PMID 26977276, 2016). "Catecholamines downregulate renal erythropoietin production and cause consecutive anemia." (PMID 26903690, 2016). "Experimental studies suggest that anabolic hormones such as testosterone, IGF-1, and thyroid hormones are able to increase erythroid mass, erythropoietin synthesis, and iron bioavailability, underlining a potential role of multiple hormonal changes in the anemia of aging." (PMID 26779261, 2015). "After the establishment of human EPO gene sequence, recombinant human EPO (rHuEPO), a structural and bio-active analogue of human EPO, has been produced as a pharmaceutical to treat patients suffering from anaemia symptoms associated with various disorders such as cancer." (PMID 26104688, 2015). "Anemia is mainly associated with a reduced production of erythropoietin (EPO) by the kidneys." (PMID 25867633, 2015). "The hematopoietic stem cell displays increasing erythropoietin (EPO) resistance with increasing age and further aging is associated with increased pro-inflammatory cytokine expression many of which contributing to EPO resistance, thereby resulting in anemia." (PMID 26045966, 2015). "The loss of erythropoietin results in decreased red blood cell production that causes anemia." (PMID 26155438, 2015). "Early dose reduction of ribavirin or use of erythropoietin may help manage anemia in susceptible patients." (PMID 26650626, 2015). "Since the patient refused bone marrow evaluation, she was initially treated with erythropoietin therapy based on the assumption that she may have an underlying refractory anemia associated with myelodysplastic syndrome or anemia of chronic disease." (PMID 26493409, 2015). "To investigate whether the anemia in Spx-treated OSM KO mice is caused by insufficient EPO production, we measured the EPO concentration in plasma by enzyme-linked immunosorbent assay (ELISA)." (PMID 25551451, 2014). "The main factors leading to the development of anaemia in this group of patients are blood loss, shortened red cell life span, vitamin deficiency, the ‘uremic milieu’, iron and erythropoietin (EPO) deficiency as well as reduced ability to bind Fe, inflammation and hyperparathyroidism." (PMID 25145866, 2014). "Thus, BAY 85-3934 is an attractive new drug candidate for the treatment of EPO-sensitive anemia, in particular anemia associated with CKD." (PMID 25392999, 2014). "The production of epolones A and B has only been reported once during investigations by OSI Pharmaceuticals for an alternative drug treatment to the use of recombinant human erythropoietin for anemia caused by chronic renal failure, cancer chemotherapy, and a variety of other disease states." (PMID 25379337, 2014). "Only 14.5% of anaemia cases in our South African study population were related to iron deficiency, confirming that normocytic normochromic anaemia of chronic inflammation (due to reduced erythropoietin production) was the biggest contributor." (PMID 25222119, 2014).
anemia (continued). "Our and the previous findings may suggest that erythropoietin deficiency, which has a major etiological role in the anemia associated with renal failure, begins even before there is evidence of deterioration in renal function." (PMID 25084095, 2014). "Patients who received erythropoietin in response to hemoglobin drop had a significantly higher probability of achieving SVR compared with those who underwent ribavirin dose reduction because of anemia (relative risk = 1.83 95% CI; 1.41-2.37)." (PMID 25948447, 2014). "Anemia relating to this inflammatory state is also associated with alterations in erythrocyte physiology, including decreased lifespan and impaired biological responsiveness to erythropoietin." (PMID 23984326, 2013). "Anemia in patients with CHF is primarily caused by a deficiency of erythropoietin (EPO) or the decreased sensitivity of the spinal cord to EPO, and the application of EPO in the treatment of CHF complicated by anemia may have a marked curative effect." (PMID 24223667, 2013). "These cytokines were measured to evaluate the extent to which they may be implicated in anaemia and anti-EPO antibody production indirectly." (PMID 23978045, 2013). "These parameters were measured to determine whether EPO rescue is associated with ameliorated anemia." (PMID 23977125, 2013). "In one strain of ACE-KO mice, there were increases in circulating levels of AcSDKP that was accompanied by a 35 mm Hg decrease in blood pressure, renal insufficiency, and unexpected normocytic anemia associated with an increase in circulating erythropoietin in response to anemia." (PMID 24167502, 2013). "If LT-mediated hemolysis anemia and erythropoiesis suppression are associated with LT-mediated pathogenic progression, then increasing erythropoiesis using EPO treatments may have ameliorative effects." (PMID 23977125, 2013). "It is known that thrombocytosis frequently accompanies the less severe anemia of iron deficiency and may be related to platelet stimulation in a manner analogous to the erythropoietin increase seen in many of the anemic states." (PMID 24349404, 2013). "The success of EPO-stimulating agents (ESAs) in increasing hemoglobin levels may be related to the cause of anemia and clinical reasons for anemia correction." (PMID 24151517, 2013). "Dietary Cu deficiency is involved in erythropoietin-resistant anemia in hemodialysis patients." (PMID 23825573, 2013). "Some investigators have speculated that the elevated levels of erythropoietin in patients with iron deficiency anemia might modestly increase platelet production by cross-reacting with the thrombopoietin receptor." (PMID 23476772, 2013). "The main cause of anemia in diabetes is suspected to be reduced erythropoietin production relative to the degree of anemia, and some researchers observed the microscopic injury of the renal tubulointerstitium, where erythropoietin is produced, in diabetic subjects." (PMID 23316229, 2012). "Furthermore, the coexistence of CHF with CKD is associated with reduced EPO production from the kidney, as well as with urinary losses of serum EPO and transferrin, which further deteriorate the anemia." (PMID 22536520, 2012). "An important question is whether EPO administration is active on the anaemia induced by imatinib, on the anaemia induced by the tumor through iron loss or inflammation, or both." (PMID 22950685, 2012). "Anemia also is an established risk factor for adverse cardiovascular outcomes, and decrease of hemoglobin (Hb) levels is highly associated with reduced production of erythropoietin (EPO)." (PMID 22952731, 2012). "In the setting of HIV/AIDS, anaemia may result from micronutrient deficiencies, immunological myelosuppression, impaired erythropoietin production, and blood loss from intestinal opportunistic disease, among other causes." (PMID 23019521, 2012). "Erythropoietin is deficient in patients with CKD-associated anemia." (PMID 22188389, 2012).
anemia (continued). "Individuals with ESRD commonly receive erythropoietin for treatment of anemia, which might be implicated in carcinogenesis and could potentially explain some of the observed excess cancer risk among individuals with ESRD." (PMID 22834953, 2012). "Via poorly understood routes, EPO also may be associated with hypertensive and thrombolytic events, and as used to treat the anemia of chemotherapy may worsen the progression of certain cancers." (PMID 22808010, 2012). "The aims of this study were to determine the associations between anemia of critical illness, erythropoietin stimulating agents (ESA), packed red blood cell transfusions and varying degrees of renal dysfunction with mortality, and ICU- and hospital length of stay (LOS)." (PMID 22924126, 2012). "Deficiency in EPO production results in anemia in humans and in animal models." (PMID 21869890, 2011). "Several other etiologic factors may also be involved in the development of HIV-associated anemia, including micronutrient deficiencies, immunological myelosuppression, impaired erythropoietin production and blood loss from intestinal opportunistic disease." (PMID 21745396, 2011). "Other etiologic factors that may be involved in the development of HIV-associated anemia include micronutrient deficiencies, immunological myelosuppression, impaired erythropoietin production and blood loss from intestinal opportunistic disease." (PMID 22145054, 2011). "However, the use of EPO in several large clinical trials for the treatment of anemia in cancer patients was associated with increased adverse events." (PMID 21943500, 2011). "Despite EPO being produced in response to hypoxia and different factors (not only hemolysis) may trigger its expression, in our setting hypoxia due to anemia seems to play a principal role as the only factor associated to EPO was Hb." (PMID 21912616, 2011). "The chief etiology of anemia in CKD is erythropoietin (Epo) deficiency." (PMID 21072151, 2010). "Low level of erythropoietin is considered as one of the causes of anemia in these pathologies." (PMID 20204172, 2009). "Hematide's lack of erythropoietin immunological cross-reactivity makes it capable of increasing haemoglobin in rats when their anaemia was caused by anti-erythropoietin antibodies that cross-react with endogenous erythropoietin following the administration of recombinant human erythropoietin." (PMID 19143750, 2009). "Of interest in this respect is the notion that the amino acid sequence homology of thrombopoietin and erythropoietin might explain thrombocytosis in children with iron-deficiency anemia." (PMID 18380894, 2008). "Several other etiologic factors may be involved in the development of HIV-associated anemia, including micronutrient deficiencies, immunological myelosuppression, impaired erythropoietin production and blood loss from intestinal opportunistic disease." (PMID 18430196, 2008). "We speculate that the inflammatory response to common childhood infections may have caused an attenuation of the EPO response to anemia." (PMID 16390553, 2006). "With the CpG island technology screening of only 20 clonal CHO cell lines was sufficient to identify lines showing very high yields of EPO, the latter being a blockbuster protein drug that is widely used to treat anaemia associated with renal failure and chemotherapy." (PMID 15935093, 2005). "Similarly, the observed anemia and lymphopenia may be consequences of systemic inflammation, reduced erythropoietin activity, and nutritional deficiencies common in chronic respiratory insufficiency." (PMID 40647611, 2025). "A possible explanation is that anemia has been linked to immune dysfunction due to inflammation-induced erythropoietin suppression, oxidative stress, and nutrient deficiencies; prior studies have also suggested that transfusions themselves may increase infection risk." (PMID 40329392, 2025).